CD276 (CD276 molecule)
Diseases named in the same sentence as CD276 in open-access papers (continued):
Sharing a sentence is not in itself a finding about the gene and the disease.
cancer (continued). "It is noteworthy that CD276 was significantly positively correlated with GARS1 in 24 types of cancer, while CD274 (PD-1) was significantly positively correlated with GARS1 in 15 types of cancer." (PMID 37404826, 2023). "Many different researchers have also shown that CD276 has a crucial role in the progression of most types of cancer." (PMID 36717836, 2023). "The results obtained showed that mutations and amplifications of CD276 were the leading types of genetic alterations, especially for the SKCM, COAD and BRCA cancer types." (PMID 36717836, 2023). "In order to detect the CD276 protein expression profiles in human normal and cancer tissues, the HPA dataset was employed." (PMID 36717836, 2023). "In a pan-cancer study, high PLAU expression was consistently associated with important immune response checkpoints such as PD-L2 and CD276/B7-H351." (PMID 36266384, 2022). "The expression of CD276 was significantly positively correlated with SRSF9 expression in most cancer types." (PMID 35069733, 2022). "The expression of CD276 was considered a promotor of metastases, and the expression of CD276 was also reported on cancer stem cells." (PMID 35563359, 2022). "CD276 showed the highest positive correlations with JMJD8 in 15 cancers, followed by LGALS9, VSIR, and TNFRSF4." (PMID 35898493, 2022). "In 4-nitroquinoline-induced mouse HNSCC, cancer stem cells (CSCs) use the immune checkpoint molecule CD276 (B7-H3) to evade immune surveillance." (PMID 36406133, 2022). "In the present study, SRSF9 expression had been shown to positively correlate with most of the 47 immune checkpoint genes in most cancers, such as CD276, CD86, CTLA-4, and CD40." (PMID 35069733, 2022). "For the analysis of 24 immune-inhibiting genes, we found that SERPINH1 expression was highly associated with CD276, TGFBI, VEGFA, HAVCR2, IL10, and ADORA2A in most cancers." (PMID 36105106, 2022). "Both GPC2 and CD276 are significantly overexpressed in multiple pediatric cancers including NB, with low or undetectable expression in normal tissues." (PMID 35852863, 2022). "Herein, we also conducted a correlation analysis between CARM1 and checkpoint genes expression and found that CARM1 expression is highly correlated with CD276 in various cancer types." (PMID 35033016, 2022). "And the negative regulatory loop between CD276, Myc, and miR‐29c‐3p affects the cytotoxicity of cancer cells against NK cells." (PMID 35028969, 2022). "The elevated expression of CD276 was also reported on cancer stem cells, promoting cancer cell proliferation and expansion of the cancer stem cell pool." (PMID 35563359, 2022). "In this study, OTUD6B expression has been unraveled to be positively correlated with most of the 47 immune checkpoint genes in almost all cancers, such as CD276, VEGFA, HMGB1, and TLR4." (PMID 36052059, 2022). "B7-H3 or CD276 are potentially associated with CRC advancement and evasion of cancer immune surveillance." (PMID 36551617, 2022). "Targeting pan-cancer antigens such as CD276 (B7-H3) has also shown tremendous success in treating various solid malignancies; however, their success is largely dependent on the level of surface antigen density." (PMID 35720306, 2022). "B7-H3, also known as CD276, is a newly discovered immune checkpoint protein, and plays a crucial role in the adaptive immune response in human cancers." (PMID 36159789, 2022). "CD276 is an immune checkpoint target highly expressed in cancer cells; it promotes M2 macrophage infiltration and decreases CD8+ T-cell infiltration." (PMID 35898493, 2022). "B7-H3 (CD276), which is a member of the B7 immunoglobulin superfamily and is highly expressed in many malignant tumors, serves as a molecular target for cancer immunotherapy." (PMID 35911706, 2022). "Among them, the CD276 gene, also known as B7-H3, is a member of the B7 ligand family and is overexpressed in various types of cancers." (PMID 35242138, 2022).
cancer (continued). "In general, the immune checkpoints seem to express with more activeness in the low-PTGS2 group, except for CD276, whose expression is always found upregulated in malignant tumors and accompanied with a poorer prognosis for cancer patients." (PMID 35432535, 2022). "A review summarized the role of CD276 in cancers, regulation mechanism and its potential therapeutic value." (PMID 36545327, 2022). "Among the upregulated immune checkpoint molecules, CD274, much more known as PD-L1, and CD276 were members of the B7 superfamily, through which cancer cells exhibit immune escape." (PMID 36467089, 2022). "CD276 is highly expressed in a wide range of human cancers, and it plays an important role in the inhibition of the T-cell function." (PMID 35327439, 2022). "CD276 plays an important role in innate immunity and T cell-mediated adaptive immunity, which is highly expressed in HCC and other cancers and is associated with poor patient prognosis." (PMID 34660693, 2021). "The results of meta-analyses indicate a relationship between increased expression of CD276 with poor survival in patients with GC and other types of malignant tumors." (PMID 34943606, 2021). "Several studies have shown that high CD276 expression in cancer cells correlates with a poor clinical prognosis." (PMID 34290311, 2021). "In this study, we report that ELK1, as the transcriptional regulator of B7 homolog 3 (B7-H3; CD276), causes the latter to be upregulated in LUAD and further promotes malignant biological behaviors in cancer cells, in particular EMT." (PMID 34970415, 2021). "Bioinformatical analysis revealed that CD276 expression by cancer cells was at least three-fold higher than that in normal tissue (fold change; 3.16)." (PMID 34680929, 2021). "B7-H3, also called CD276, is overexpressed in many malignant tumors and closely related to the increased metastasis, recurrence, resistance to therapy, and poor prognosis of malignant tumors." (PMID 34131111, 2021). "CD276 (also known as B7–H3, an immune checkpoint molecule) is aberrantly overexpressed in many cancers." (PMID 33431797, 2021). "Our results, consistent with the previous studies, indicated that CD276, IL1B, LYVE1 and VEGFC are associated with cancer progression." (PMID 33995379, 2021). "An anti-CD276 monoclonal antibody (mAb) was developed for cancer therapy, which, under the name Enoblituzumab, is undergoing phase 1–2 clinical trials, that demonstrate the antitumor activity of the drug and an acceptable safety profile." (PMID 34943606, 2021). "We also explored the correlation of CD276 expression with survival and found CD276 expression is significantly correlated with survival probability in a wide range of cancer types (p < 0.05)." (PMID 33842369, 2021). "CD276 mRNA is widely expressed in many tissues and notably aberrantly expressed in various types of cancer." (PMID 33431797, 2021). "B7-H3, also known as CD276, is a transmembrane protein frequently expressed by cancer cells, and is considered an immune-checkpoint molecule exploited by cancer cells to escape immune system recognition." (PMID 35069581, 2021). "On the other hand, IGF-1R expression positively correlates with the expression of NRP1 and CD276 in the majority of 33 cancer types." (PMID 34804946, 2021). "CD276 (B7-H3) is one of the B7 superfamily molecules that correlates with prognosis in various cancer types." (PMID 31998416, 2020). "Correlation analyses between YIF1B and checkpoint gene expression found a high correlation (P<0.05) with tumor necrosis factor (TNF)-related immune genes (TNFRSF4, 8, 14, 18) and CD276 (B7H3) in various cancer types." (PMID 32648580, 2020). "Overexpression of CD276 is a common mechanism by which tumors evade the adaptive immune response in numerous types of cancer." (PMID 33008419, 2020). "Meanwhile, CD276 is also related to invasiveness and the epithelial-to-mesenchymal transition pathway in cancer cells." (PMID 31998416, 2020).
cancer (continued). "The response of CD276 and PD-L1 to pharmacological or genetic perturbation in this range of cancer cell lines highlights the translatability of these pathways in different cell models." (PMID 32874188, 2020). "SPARC expression was positively and significantly correlated to CD276 (B7-H3) in all the eight cancer types." (PMID 33240930, 2020). "Herein, expression of the CD276 protein was observed in more than 90% of cases with this extremely rare and high malignant carcinoma." (PMID 31998416, 2020). "Expression of membrane CD276 (mB7H3) has been reported on dendritic cells, monocytes, activated T cells, and various carcinoma cells." (PMID 32953890, 2020). "For example, CD276, a highly conserved cell-surface protein, is found broadly overexpressed by multiple malignancies on both cancer cells and blood vessels." (PMID 35582580, 2019). "B7H3 (also known as CD276, an immune checkpoint molecule) is aberrantly overexpressed in many types of cancer, and such upregulation is generally associated with a poor clinical prognosis." (PMID 30035102, 2018). "In line with their immunosuppressive phenotype, several molecules, known to be linked to cancer progression and immune evasion, were highly expressed (>80%: CD47, CD274, CD276, and Indoleamine 2,3 dioxygenase-1)." (PMID 26618628, 2015). "B7H3 (CD276), an immunoregulatory molecule known for its role in immune evasion by transmitting inhibitory signals to T lymphocytes, has garnered significant attention in recent years as a promising target for cancer immunotherapy." (PMID 40243697, 2025). "The presented mechanism may thus illustrate a novel way for CD276 to induce angiogenesis, metastasis, and cancer progression in MB." (PMID 40801642, 2025). "In several types of cancer, CD276 is often overexpressed and mainly affects T cell responses." (PMID 40161494, 2025). "CD276 expression was negatively with UBA6 only in a few cancers such as BRCA, COAD and READ." (PMID 40046044, 2025). "Additionally, targeting CD276 reduced cancer cell proliferation, migration, and angiogenic abilities in endothelial tube formation assays." (PMID 40214484, 2025). "Additionally, we found rather consistent and uniform upregulation of CD276 (B7-H3) in both ADCs and NENs across sites, further positioning B7-H3 as a versatile precision target across cancer." (PMID 39874041, 2025). "Inspired by the DNA damage-inducing capability of cmLumiOpto, we hypothesize that combining the cancer mitochondria-targeted cmLumiOpto, delivered via CD276 mAb-Exo-AAV, with PARPi will lead to a synergistic effect." (PMID 41462289, 2025). "Furthermore, the expression of GPX4 was closely associated with MHC molecules, immune activation genes, and immunosuppressive genes such as HLA-A, HLA-B, CD160, TNFRSF18, TNFRSF4 and CD276 in most cancer types." (PMID 41142608, 2025). "In addition, a cluster of genes associated with epithelial and cancer cells (for example, CDH1, EPCAM, BIRC5 and CD276) was significantly downregulated in resected tumors with nivolumab/relatlimab-induced MPR." (PMID 38689060, 2024). "Amazingly, CD276 expression was positively correlated with PTBP1 expression in most cancers." (PMID 38918441, 2024). "Also, CD274 (PD-L1) showed positive association with SIRPG, whereas RATE1E, CD276 and VEGFA expression seemed to be negatively correlated with SIRPG expression in a subset of TCGA cancers." (PMID 38833156, 2024). "Nevertheless, the role of CD276 in tumorigenesis and immune responses remains unclear in several types of cancer." (PMID 39911580, 2024). "Moreover, RBMX was significantly positively associated with CD200, CD276, and butyrophilin like 2 (BTNL2) expression in most types of cancer." (PMID 38214653, 2024). "CD276 expression in bladder urothelial cell carcinoma and para-cancer tissues." (PMID 39319055, 2024).
cancer (continued). "In conclusion, CD276 has been discovered to be a potential prognostic biomarker for pan-cancer." (PMID 39766794, 2024). "CD276/B7-H3 belongs to the B7 family and is considered a promising target for cancer immunotherapy." (PMID 39367484, 2024). "Additionally, the expression of CD276 was found to be elevated in cold tumors across all five cancer types, while NT5E exhibited higher expression levels in cold tumors of the CESC, PAAD, SARC, and SKCM groups." (PMID 39911580, 2024). "Notably, CD276, known to regulate cell proliferation, invasion, and migration in cancers, emerged as a key factor in this resistance landscape." (PMID 38254897, 2024). "As a pan-cancer antigen, we found that CD276 was highly expressed in many cancer cell lines." (PMID 38978106, 2024). "Furthermore, TOP1 was found to regulate several T cell regulatory genes including CD274 and CD276, which serve as markers of limiting T-cell effector response or anti-cancer immunity." (PMID 39156107, 2024). "CD276 is an immunomodulatory protein that promotes cancer cell growth." (PMID 39319055, 2024). "Recently, B7-H3 (CD276) has emerged as a promising target for a variety of cancers." (PMID 38709075, 2024). "The expression profiles of cancer-related checkpoints showed that the majority of checkpoint-target genes had low expression levels in the high-risk group, and only TNFRSF25, TNFRSF4, TNFRSF14, TNFRSF18, and CD276 were upregulated in the high-risk group." (PMID 37190215, 2023). "Recent report indicates that targeting CD276 may enhance ICB-based immunotherapy in HNSC because it overexpressed in cancer stem cells and could be utilized to escape attacking from CD8+ T cells." (PMID 37504302, 2023). "Clinical studies of combination therapy with anti-CD276 antibodies and chemotherapy or other checkpoint inhibitors may demonstrate that targeting CD276 in cancer is a synergistic treatment approach." (PMID 37373167, 2023). "The resistance observed was not attributable to a lack of CD276 expression, as all tested cancer cell types displayed similar CD276 mRNA levels in the Cancer Dependency Map (DepMap) dataset and comparable cell surface protein levels as assessed by flow cytometry." (PMID 38019654, 2023). "B7-H3 (B7 homolog 3 protein) (CD 276), an immune checkpoint molecule that is widely expressed on activated T cells, monocytes, and dendritic cells, is overexpressed in multiple cancer types, thus making it a promising immunotherapy target." (PMID 37835416, 2023). "We speculate that he EMT process may be the link between ANXA2 and CD276, and CD276 may be the key factor for breakthrough in cancer immunotherapy targeting ANXA2, which needs more research to prove." (PMID 36713082, 2023). "Moreover, we report, for the first time, the association of IL12RB1, CA11, CD276, and APBB1IP with cancer-associated inflammation." (PMID 37228491, 2023). "Subsequently, we researched the prognostic value of CD276 in cancer patients." (PMID 36717836, 2023). "Finally, monoclonal antibodies against CD276 are currently in phase I clinical trials, and further optimization of cancer immunotherapy approaches are required in humans." (PMID 36717836, 2023). "In addition, recent studies have demonstrated that proliferation, migration, invasion, and transition from endothelial to mesenchymal (EMT) are facilitated by CD276 in cancer cells." (PMID 37974070, 2023). "Besides, there was a robust positive relationship between SNAI2 and NRP1, and CD276 in most of the TCGA cancers." (PMID 37251370, 2023). "CD276 expression in different tumors and the corresponding normal tissues was investigated on the basis of TCGA and GTEx datasets, and we discovered that CD276 was highly expressed in 30 types of cancer, including ACC, BLCA and BRCA, but expressed at low levels in CESC, LAML and PCPG." (PMID 36717836, 2023). "Anti-CD276 antibodies eliminate cancer stem cells in a CD8+ T-cell-dependent manner." (PMID 37190215, 2023).
cancer (continued). "Finally, the DSS analysis revealed that CD276 serves as a hazardous element in numerous types of cancer, including BLCA, HNSC, ACC, COAD, LGG, MESO, PAAD and UVM." (PMID 36717836, 2023). "Moreover, it was found that the DNA methylation level of CD276 was observably decreased in almost all types of cancers in the UALCAN database, including BLCA, LIHC, LUAD, LUSC, PCPG and TGCT, and these decreases were statistically significant." (PMID 36717836, 2023). "Notably, immune checkpoints TGFB1 and CD276 were significantly positively correlated in 25 types of cancers." (PMID 37504302, 2023). "In addition, CD276 was also shown to affect the glycolytic ability of cancer cells through regulating the activity of metabolic enzymes." (PMID 36717836, 2023). "Combined with our finding that SNAI2 was strongly related to the expression of CD276, NRP1, and CD44 in many cancer types, we speculated that the potential association between SNAI2 and CD276, CD44, or NRP1 was promising for our further studies." (PMID 37251370, 2023). "CD276 (also known as B7-H3) is one of the most important immune checkpoints of the CD28 and B7 superfamily, and its abnormal expression is closely associated with various types of cancer." (PMID 36717836, 2023). "Soluble CD276, which is cleaved from the surface by a matrix metallopeptidase or produced through the alternative splicing of the intron, has also been detected in the serum of cancer patients, suggesting its potential as a noninvasive biomarker." (PMID 37373167, 2023). "Finally, using the TISDB database, it was found that CD276 expression was negatively associated with Act CD8 cells, Act B cells and Tem CD4 cells in most types of cancer, but positively correlated with macrophages and neutrophils." (PMID 36717836, 2023). "It has been shown that CD276 is able to inhibit the function of T cells, and that this gene may potentially be a promising immunotherapy target for different types of cancer." (PMID 36717836, 2023). "Studies have shown that targeting CD276 might reduce cancer stem cell (CSC) immune escape in neck squamous cell carcinoma (HNSCC)." (PMID 37124611, 2023). "With a preferential expression on cancer cells, CD276 could be considered an attractive target for cancer immunotherapy." (PMID 35662721, 2022). "Notably, it was demonstrated that CD276 mRNA levels were overexpressed in various types of cancer in comparison with matched normal tissues." (PMID 36555714, 2022). "CD276 (B7-H3) is an immune checkpoint molecule of special interest in cancer research." (PMID 35884502, 2022). "According to a recent study, CD276 could mediate the immune escape in carcinoma stem cells, making it an attractive target for antibody-based immunotherapy." (PMID 35242138, 2022). "CD276 is overexpressed by several human cancers and its expression correlates with poor outcomes." (PMID 34680929, 2021). "Notably, the expression of CTHRC1 was positively correlated with ICP gene CD276, which was identified a promising therapeutic target for malignant tumors." (PMID 34702252, 2021). "However, compared to PDL1, the cellular mechanisms that regulate CD276 expression in cancer cells are poorly understood." (PMID 33431797, 2021). "NB-derived EV were subjected to flow cytometric analysis and confirmed that some of these proteins, including fibronectin, the cancer stem cell marker CD133, the tumor associated antigen CD147 and the immunosuppressive molecule B7H3 (CD276), are expressed on their surface." (PMID 33921337, 2021). "Moreover, higher expression levels of CD276 has been found to be correlated with poorer prognosis in cancer patients." (PMID 33842369, 2021). "Results from most recent studies indicate CD276 could be a promising therapeutic target for malignant tumors." (PMID 33842369, 2021). "CD276 has become an attractive target for cancer immunotherapy." (PMID 34298996, 2021).